OR6B1 (olfactory receptor family 6 subfamily B member 1)
Description:
Odorant receptor.
Synonyms: OR7-3; OR7-9
Tractability: Antibody: UniProt places it where antibodies can reach, with medium confidence; UniProt predicts a signal peptide or a membrane-spanning region; its Gene Ontology location is reachable by antibodies, with medium confidence.
Gene: Protein-coding gene on chromosome 7 (144,000,320 to 144,008,793, forward strand). Ensembl gene ENSG00000221813.
Subcellular location: Cell membrane
Pathways (Reactome):
Sensory Perception: Expression and translocation of olfactory receptors
Gene Ontology:
Molecular function: protein binding; olfactory receptor activity; G protein-coupled receptor activity
Biological process: detection of chemical stimulus involved in sensory perception of smell; G protein-coupled receptor signaling pathway
Cellular component: plasma membrane; membrane
Genetic constraint (gnomAD): Loss-of-function variants: 16 observed, 17.83 expected, observed/expected ratio (o/e) 0.9, 90% interval 0.61 to 1.36. The upper end of that interval is the gene's LOEUF score, 1.36, which puts it in group 5 of 6, group 1 being the genes least tolerant of losing a copy. Missense variants: 384 observed, 403.04 expected, observed/expected ratio (o/e) 0.95, 90% interval 0.88 to 1.04. Synonymous variants: 139 observed, 151.26 expected, observed/expected ratio (o/e) 0.92, 90% interval 0.8 to 1.06.
Homologues: Orthologues: macaque OR6B1 (97% identical), mouse Or6b1 (93% identical), rat Or6b1 (92% identical), rabbit OR6B1 (92% identical), dog OR6B1 (91% identical), guinea pig OR6B1 (88% identical). Paralogues in human: OR6A2 (57% identical), OR6Y1 (54% identical), OR10A4 (46% identical), OR10C1 (46% identical), OR10G6 (44% identical), OR2D3 (44% identical), OR5V1 (44% identical), OR2D2 (44% identical), OR10A5 (43% identical), OR10A7 (43% identical), OR13C3 (43% identical), OR13C8 (43% identical), and 80 more.
Diseases named in the same sentence as OR6B1 in open-access papers:
OR6B1 is named in the same sentence as 2 diseases in open-access papers, as found by Europe PMC text mining. Sharing a sentence is not in itself a finding about the gene and the disease.
gastric cancer (1 paper, 2025). A primary or metastatic malignant neoplasm involving the stomach.
OR6B1 also shares sentences with these, for which no sentence is quoted: cardia cancer (1 paper).